TTR (transthyretin)
Diseases named in the same sentence as TTR in open-access papers (continued):
Sharing a sentence is not in itself a finding about the gene and the disease.
amyloidosis (continued). "Onpattro treats hereditary transthyretin-mediated amyloidosis by silencing the mutant TTR gene, demonstrating the potential of RNA interference therapeutics." (PMID 40768059, 2025). "After this trial, many siRNA-based drugs were tested for various diseases, and in 2018, the first siRNA drug for patients having transthyretin-mediated amyloidosis was approved." (PMID 39744758, 2025). "The diagnosis of severe cardiac wild-type transthyretin amyloidosis was finally confirmed, characterized by both focal and diffuse amyloid deposition patterns." (PMID 39963604, 2025). "Atrial fibrillation (AF) occurred more commonly in amyloidosis (57.6%) than in sarcoidosis (45.7%), aligning with previously reported AF rates approaching 70% in wild-type transthyretin amyloidosis." (PMID 40943826, 2025). "Most amyloid fibrils are rare or very rare, the most frequent types of amyloidosis that can be found in humans are AL (derived from immunoglobulin light chain), wild-type and variant ATTR (derived from transthyretin), and AA (derived from serum amyloid A)." (PMID 40892784, 2025). "Amyloidosis can arise from various types of amyloid proteins, but in Europe, the most prevalent forms are amyloid light-chain (AL) and transthyretin (ATTR) amyloidosis." (PMID 40095730, 2025). "Inotersen promotes the degradation of TTR mRNA to reduce the amount of circulating transthyretin, thereby reducing amyloid deposits." (PMID 41465141, 2025). "Immunoglobulin light chain (AL) and wild-type transthyretin (ATTRwt) amyloidosis, while sharing similar clinical presentations, require distinct treatments." (PMID 40809950, 2025). "The first FDA-approved LNP delivery system using ionizable lipids (e.g., 1,2-dilinoleyl-N,N-dimethyl-3-aminopropane) was designed to use RNAi to treat transthyretin-mediated amyloidosis." (PMID 41210587, 2025). "Vutrisiran, inotersen, patisiran are RNA therapeutics that target transthyretin for degradation and subsequently halt the progression of amyloidosis." (PMID 41166051, 2025). "Wild-type transthyretin (TTR) amyloid cardiomyopathy (ATTRwt-CM) is an age-related disease characterized by amyloid deposition in the myocardium." (PMID 40736438, 2025). "Amyloidosis is a condition, which can be inherited or acquired, in which misfolded amyloid deposits of transthyretin accumulate in tissues and organs, including the heart, interfering with normal function." (PMID 41166051, 2025). "The predominance of wild-type transthyretin amyloidosis patients in our cohort, with only a small number of AL amyloidosis cases, limits the generalizability of our findings to all CA subtypes." (PMID 40675021, 2025). "It reduces mutant and wild-type transthyretin protein production by targeting the 3′ untranslated region of transthyretin mRNA for the treatment of hereditary transthyretin-mediated amyloidosis." (PMID 40243658, 2025). "The disease can be caused by different types of amyloid proteins, with the most common being AL (light chain) amyloidosis and ATTR (transthyretin) amyloidosis." (PMID 40448354, 2025). "A major milestone was achieved with the approval of Patisiran (ONPATTRO®) in 2018, the first FDA-approved liver-targeted siRNA therapeutic to treat hereditary transthyretin (TTR) amyloidosis." (PMID 41516128, 2025). "Hereditary-TTR amyloidosis (h-ATTR) affects younger ages, with an episode of cardiomyopathy, polyneuropathy, or mixed depending on the TTR gene mutation." (PMID 39857728, 2025). "There are several types of systemic amyloidosis, including amyloid formed from immunoglobulin light chain (AL) and amyloid transthyretin (ATTR) amyloidosis." (PMID 40951054, 2025). "In cardiac amyloidosis, a substantial majority of the patients, 70.4% (88 out of 125), were treated with Tafamidis, a medication specifically targeting transthyretin stabilization to mitigate the progression of amyloidosis." (PMID 40943826, 2025).
amyloidosis (continued). "In this trial, LNP was used to encapsulate sgRNA and Cas9 mRNA targeting the TTR gene for the treatment of transthyretin amyloidosis." (PMID 41210587, 2025). "It encompasses a heterogenous group of disorders, most notably light-chain (AL) and transthyretin (ATTR) amyloidosis, which differ significantly in pathophysiology and prognosis." (PMID 41517562, 2025). "The heart is commonly infiltrated by two types of amyloids: immunoglobulin light chain (AL) amyloidosis and transthyretin (ATTR) amyloidosis." (PMID 40142887, 2025). "Amyloid light chain (AL) and transthyretin amyloidosis (ATTR)-induced cardiomyopathy are life-threatening protein misfolding disorders characterized by amyloid fibril deposition in the heart, which significantly impairs cardiac function." (PMID 40889301, 2025). "Transthyretin (TTR) amyloidosis is a progressive, debilitating, and eventually fatal disease that is under-recognized and underdiagnosed in Asian patients." (PMID 40406766, 2025). "Tafamidis is a clinically approved drug for transthyretin-mediated amyloidosis, yet its molecular interactions with biological macromolecules such as DNA remain unexplored." (PMID 40861951, 2025). "Patients with hereditary ATTR amyloidosis are reported to have decreased serum TTR concentrations after the onset of amyloidosis, and the production and survival ratio of wild-type TTR to mutant TTR is generally about 1:1." (PMID 40429804, 2025). "TTR is a protein mainly produced in the liver, and liver transplantation (LT) for the treatment of TTR amyloidosis has shown favorable results for FAP patients with the V30M mutation, with a five-year survival rate of 100%." (PMID 40406766, 2025). "Vutrisiran (Amvuttra®) reduces transthyretin (TTR) protein levels by targeting TTR mRNA to treat hereditary transthyretin-mediated amyloidosis." (PMID 41155941, 2025). "For those 29 individuals, the median time from first mention of TTR amyloidosis to diagnosis was 49 days (IQR 10 days-296 days)." (PMID 41282679, 2025). "The diagnosis of ATTRwt amyloidosis was confirmed, and treatment with a TTR tetramer stabilizer, tafamidis, was initiated." (PMID 40330419, 2025). "In accordance with the National Program for TTR amyloidosis, at that moment, the patient was started on specific therapy with tafamidis 20 mg daily, for stage I polyneuropathy." (PMID 40429539, 2025). "Vutrisiran (Amvuttra, Alnylam Pharmaceuticals, Cambridge, MA, USA) is another siRNA drug approved by the FDA and the EMA for therapy in patients affected by TTR amyloidosis." (PMID 40755967, 2025). "After discussion of the case in our multidisciplinary amyloidosis board, we began disease-modifying treatment with tafamidis, an established TTR stabilizer, which had previously shown efficacy in patients with vATTR for cardiopathy and neuropathy." (PMID 40681261, 2025). "The remaining 52 patients, one patient with inherently TTR‐amyloidosis, and the other patient with amyloid‐A amyloidosis were excluded from the analysis." (PMID 39873364, 2025). "In siRNA-based therapeutics, patisiran (Onpattro) became the first FDA-approved siRNA drug in 2018, targeting TTR mRNA to treat hereditary transthyretin-mediated amyloidosis (hATTR) by reducing toxic protein accumulation." (PMID 41153385, 2025). "For example, the ASO drug Wainua treats amyloidosis polyneuropathy by suppressing transthyretin (TTR) production." (PMID 40677784, 2025). "Aggregation of transthyretin (TTR) causes TTR cardiomyopathy and polyneuropathy through amyloidosis." (PMID 40816471, 2025). "Each amyloid type name is referred to as the letter A, followed by the abbreviation of the protein type: amyloid light chain—primary (AL), serum amyloid A protein—secondary (AA), transthyretin amyloidosis (ATTR), and wild-type ATTR." (PMID 38829477, 2025).
amyloidosis (continued). "Patients undergoing a transcatheter aortic valve replacement (TAVR) should be evaluated for cardiac amyloidosis, given that transthyretin (ATTR) amyloidosis has been identified in 7–19% of such cases." (PMID 40427056, 2025). "TTR amyloidosis occurs when the TTR tetramer dissociates into monomers, which then misfold and aggregate into insoluble amyloid fibrils." (PMID 40697338, 2025). "TTR amyloidosis is a gradually progressive condition resulting from the accumulation of misfolded TTR protein in tissues." (PMID 40006568, 2025). "TTR amyloidosis is subdivided into two main categories: hereditary amyloidosis (h-ATTR), caused by mutations in the transthyretin gene, and wild-type amyloidosis (w-ATTR), caused by deposition of normal transthyretin, typically seen in older patients." (PMID 41024906, 2025). "Transthyretin (ATTR) amyloidosis is a rare, progressive disease characterized by the abnormal accumulation of amyloid deposits, composed of misfolded transthyretin protein, in the body’s organs and tissues." (PMID 39819351, 2025). "In ATTRwt amyloidosis, the protein precursor TTR is targeted for treatment, and the patient is managed for heart failure and rhythm disorders as well." (PMID 39897254, 2025). "These therapies aim to either stabilise the TTR tetramer, silence TTR production, or actively promote amyloid clearance." (PMID 40429476, 2025). "For targeting Transthyretin‐mediated amyloidosis (TTR), a rare progressive disease, siRNA has shown a significant reduction of TTR mRNA." (PMID 40390497, 2025). "Patisiran uses siRNA to inhibit abnormal transthyretin (TTR) production, caused by a mutation in the TTR gene, to treat the resulting disease hereditary transthyretin-mediated amyloidosis (hATTR)." (PMID 39833468, 2025). "In 2018, the first siRNA‐based medication, “Patisiran” (Onpattro), was approved for treating transthyretin‐mediated amyloidosis, representing a major milestone in RNAi therapy." (PMID 41392379, 2025). "Tafamidis is an FDA-approved therapeutic agent designed to stabilize the native tetrameric structure of TTR and delay disease progression in transthyretin amyloidosis patients." (PMID 41233352, 2025). "In transthyretin (ATTR) amyloidosis, tafamidis is now the first-line therapy, stabilizing transthyretin to prevent further fibril deposition." (PMID 40137102, 2025). "In patients with normal serum protein electrophoresis, a PYP cardiac scintigraphy scan should be performed, as it has a 99% positive predictive value for TTR amyloidosis." (PMID 41024906, 2025). "Diflunisal, a TTR stabilizer, is suitable for mild stages of the condition, but has limited efficacy against established amyloid deposits." (PMID 41388420, 2025). "Liver transplantation to prevent the expression of mutant TTR protein was the first intervention to demonstrate improved rates of long-term survival in patients with early-onset ATTR p.V50M (V30A) amyloidosis." (PMID 40433205, 2025). "The lipid nanoparticle (LNP) coated delivery of siRNA molecules to the hepatocytes has been clinically proven to be highly effective for the treatment of hypercholesterolemia and transthyretin-induced amyloidosis." (PMID 41355988, 2025). "For example, Patisiran, a siRNA therapeutic targeting transthyretin, has been approved by the FDA for treating hereditary transthyretin-mediated amyloidosis, marking a significant milestone in RNAi therapy." (PMID 39776807, 2025). "Amyloid transthyretin-derived (ATTR) amyloidosis is a degenerative, systemic disease characterized by transthyretin fibril deposition in organs like the heart, kidneys, liver, and skin." (PMID 41402329, 2025). "Meanwhile, wild-type TTR amyloidosis (wt-ATTR) most frequently affects elderly men, who begin with RCM." (PMID 39857728, 2025). "We report a case of dual amyloidosis with Alzheimer's disease and wild-type transthyretin (ATTRwt) amyloidosis." (PMID 40330419, 2025).
amyloidosis (continued). "For example, Onpattro, an LNP-formulated siRNA therapy, has been approved for treating hereditary transthyretin-mediated amyloidosis 85, showcasing the clinical viability of LNP-based therapies." (PMID 39776807, 2025). "Significant advances in the treatment of transthyretin (ATTR) amyloidosis has led to an evolving understanding of the epidemiology of this condition." (PMID 39819351, 2025). "The third therapeutic modality for addressing TTR amyloidosis involves antiamyloid antibodies, 50 which are specifically designed to bind to and extract misfolded TTR and amyloid deposits from affected organs and tissues." (PMID 40697338, 2025). "The condition most commonly arises from either immunoglobulin light chain (AL) amyloidosis or transthyretin (ATTR) amyloidosis, the latter of which includes hereditary (variant) and wild-type forms." (PMID 40855139, 2025). "CRISPR-Cas treatments for transthyretin (TTR) amyloidosis aim to target the underlying genetic mutation in the TTR gene, which causes misfolded transthyretin proteins to accumulate in organs like the heart and nerves." (PMID 41211267, 2025). "It was Patisiran (Onpattro®), developed by Alnylam Pharmaceuticals as an siRNA–LNP complex designed to reduce transthyretin protein formation and to treat hereditary transthyretin-mediated amyloidosis, representing a milestone in nucleic acid therapeutics." (PMID 40282336, 2025). "The presented case also suggests MGUS as an additional candidate screening criterion, consistent with recent evidence of a higher prevalence of MGUS among not only patients with immunoglobulin light chain amyloidosis but also those with TTR amyloidosis." (PMID 39703588, 2024). "The two most prevalent systemic amyloidosis types affecting the heart in the vast majority (>95%) of cases are immunoglobulin light chain (AL) amyloidosis and transthyretin (TTR) amyloidosis (ATTR amyloidosis)." (PMID 39685666, 2024). "Of these, systemic AL amyloidosis (AL) due to the deposition of misfolded immunoglobulin light chains and wild-type transthyretin amyloidosis (wtATTR), due to misfolded native transthyretin deposition, are the two commonest types." (PMID 38275011, 2024). "The treatment of amyloidosis by TTR aims to support complications, manage heart failure and prevent disease progression." (PMID 39157068, 2024). "Future analysis of NAC, as a therapeutic approach to prevent TTR-amyloidosis, should therefore focus on its effect in the interstitial fluids rather than plasma." (PMID 39615680, 2024). "Transthyretin (TTR)-amyloidosis is a progressive systemic human disorder characterized by the accumulation of amyloid fibrils of the extracellular protein TTR in various tissues." (PMID 39615680, 2024). "Mass spectrometry on a paraffin block yielded a peptide pattern consistent with transthyretin (TTR) amyloidosis (also known as ATTR)." (PMID 38576771, 2024). "Transthyretin amyloidosis (ATTR), impacting both the nervous system and heart, results from the abnormal accumulation of transthyretin (TTR), causing rare but significant morphological and functional changes in tissues." (PMID 39204382, 2024). "The four approved oligonucleotides are indicated for various types of disorders, including amyotrophic lateral sclerosis, geographic atrophy, primary hyperoxaluria type 1, and polyneuropathy of hereditary transthyretin-mediated amyloidosis." (PMID 38399458, 2024). "On the other hand, an unfavorable trait of transthyretin is its tendency to form amyloid fibers, which are deposited in the tissues and can lead to the development of amyloid diseases." (PMID 38392198, 2024). "The primary objective of this research was to assess the effectiveness of a single ascending dosage of NTLA-2001 in treating patients with polyneuropathic hATTR amyloidosis through TTR editing and knockout in human hepatocytes." (PMID 38362491, 2024).
amyloidosis (continued). "SRA proteins transthyretin, complement C3, albumin, fibrinogen, α-2-macroglobulin, fibronectin 1, and α-1-antitrypsin have been related to amyloidosis." (PMID 37902886, 2024). "The two most frequent systemic amyloidosis types affecting the heart in the vast majority (>95%) of cases are immunoglobulin light chain (AL) amyloidosis and transthyretin (TTR) amyloidosis (ATTR amyloidosis)." (PMID 39685666, 2024). "Transthyretin amyloidosis (ATTR) occurs when the transthyretin (TTR) protein, which is typically synthesized by the liver, undergoes pathological misfolding and aggregates into amyloid fibrils and is deposited in multiple tissues, causing irreversible damage." (PMID 39451564, 2024). "The most common systemic amyloidosis that lead to cardiac involvement are light chain (AL) and transthyretin (ATTR) amyloidosis." (PMID 39407933, 2024). "Congo red staining demonstrated foci of amyloid deposition, and subtyping by mass spectrometry was consistent with TTR amyloidosis." (PMID 39703588, 2024). "Transthyretin amyloidosis: The main function of Transthyretin (prealbumin) produced by the liver is to transport thyroxine and retinol." (PMID 38111336, 2024). "Our previous study using the proximity ligation assay demonstrated the colocalization of ANF and TTR in amyloid deposits in the AS." (PMID 39125745, 2024). "The application of lipid‐based nanoparticles for COVID‐19 vaccines and transthyretin‐mediated amyloidosis treatment have highlighted their potential for translation to cancer therapy." (PMID 38054651, 2024). "ALN-TTRsc for the treatment of transthyretin in mediated amyloidosis and ALN-PCS02 for treating hypercholesterolemia is currently in clinical trial by Alnylam Pharmaceuticals." (PMID 38276502, 2024). "Hereditary ATTR (hATTR) amyloidosis, a less common form of ATTR amyloidosis, can be caused by more than 100 different pathogenic mutations in the TTR gene." (PMID 38362491, 2024). "Tafamidis and diflunisal are small molecules that stabilize TTR within the homotetramer to prevent destabilization and dissociation into amyloid fibrils, therefore preventing the progression of TTR amyloidosis." (PMID 38668084, 2024). "In the peripheral nerve, it is believed that an early disruption of blood-nerve barrier facilitates entry of circulating TTR and amyloid deposition." (PMID 38410247, 2024). "In 2018, the world's first siRNA-based drug, Patisiran, was approved for the treatment of hereditary transthyretin-mediated amyloidosis, and another siRNA-based drug, Givosiran, was approved in 2020 for adults with acute hepatic porphyria." (PMID 39226164, 2024). "Especially, the subtype of transthyretin amyloidosis is an underdiagnosed comorbidity found in up to 15% in the overall cohort of AS, and in up to 30% of patients with low-flow, low-gradient AS." (PMID 38999259, 2024). "Other reasons included unexplained HF combined with extracardiac signs and symptoms of TTR amyloidosis (32%), family screening (3%) and incidental findings (4%)." (PMID 39460551, 2024). "Generic cross-β structural motif was also reported for pathogenic fibrils of non-NDD amyloidoses as exemplified by amyloid light-chain (AL) amyloidosis, transthyretin (TTR) amyloidosis." (PMID 38374092, 2024). "We describe here the first case of exposure to patisiran treatment, a small interfering RNA molecule, during early pregnancy of a 36-year-old woman with symptomatic hereditary transthyretin-related amyloidosis." (PMID 38532802, 2024). "Inotersen, a 2′-O-methoxyethyl-modified ASO targeting both wild-type and mutant TTR in the liver, demonstrated positive outcomes in a 15-month phase 3 study for hereditary TTR amyloidosis polyneuropathy." (PMID 39204382, 2024). "HybridTTR (hTTR) tetramers are found in heterozygous individuals that expressboth wild type TTR (wt-TTR) and mutant TTR (mTTR) forms of the protein,and these states display increased rates of amyloidosis." (PMID 39057193, 2024).